OR14J1 (olfactory receptor family 14 subfamily J member 1)
Description:
Odorant receptor.
Synonyms: OR5U1; hs6M1-28; OR6-25; bA150A6.4
Tractability: Small molecule: it belongs to a druggable protein family. Antibody: its Gene Ontology location is reachable by antibodies, with high confidence; UniProt places it where antibodies can reach, with medium confidence; UniProt predicts a signal peptide or a membrane-spanning region.
Gene: Protein-coding gene on chromosome 6 (29,301,701 to 29,313,017, forward strand). Ensembl gene ENSG00000204695.
Subcellular location: Cell membrane
Pathways (Reactome):
Sensory Perception: Expression and translocation of olfactory receptors; Olfactory Signaling Pathway
Gene Ontology:
Molecular function: odorant binding; olfactory receptor activity; G protein-coupled receptor activity
Biological process: sensory perception of smell; detection of chemical stimulus involved in sensory perception of smell; G protein-coupled receptor signaling pathway
Cellular component: plasma membrane; membrane
Genetic constraint (gnomAD): Loss-of-function variants: 1 observed, 1.06 expected, observed/expected ratio (o/e) 0.94, 90% interval 0.26 to 1.89. That is too few expected variants to judge how well the gene tolerates losing a copy. Missense variants: 366 observed, 400.57 expected, observed/expected ratio (o/e) 0.91, 90% interval 0.84 to 1. Synonymous variants: 138 observed, 150.44 expected, observed/expected ratio (o/e) 0.92, 90% interval 0.8 to 1.06.
Homologues: Orthologues: chimpanzee OR14J1 (99% identical), macaque OR14J1 (96% identical), rabbit OR14J1 (88% identical), dog OR14J1 (82% identical), mouse Or14j1 (80% identical), rat Or14j1 (79% identical), guinea pig OR14J1 (77% identical). Paralogues in human: OR14A16 (49% identical), OR14L1 (48% identical), OR14A2 (47% identical), OR14K1 (47% identical), OR14I1 (46% identical), OR14C36 (45% identical), OR9I1 (42% identical), OR5A1 (41% identical), OR5AU1 (40% identical), OR5AS1 (40% identical), OR5B21 (40% identical), OR5I1 (40% identical), and 84 more.
Diseases named in the same sentence as OR14J1 in open-access papers:
OR14J1 is named in the same sentence as 2 diseases in open-access papers, as found by Europe PMC text mining. Sharing a sentence is not in itself a finding about the gene and the disease. The quoted sentences say what the papers report.
Insulin resistance (1 paper, 2025). Increased resistance towards insulin, that is, diminished effectiveness of insulin in reducing blood glucose levels. "One of these regions, located on chromosome 6p22.1 (closest annotated gene OR14J1), exhibited interaction effects with smoking on insulin resistance (HOMA‐IR)." (PMID 40719081, 2025).
OR14J1 also shares sentences with these, for which no sentence is quoted: autistic spectrum disorder (1 paper).